CDC25A (cell division cycle 25A)
Diseases named in the same sentence as CDC25A in open-access papers (continued):
Sharing a sentence is not in itself a finding about the gene and the disease.
colon carcinoma (20 papers, 2002 to 2025). "Counterintuitively, in colon cancer and glioblastoma, Cdc25a upregulation after inhibition of miR-21 resulted in decreased rather than increased tumor proliferation." (PMID 35572197, 2022). "In expansion to DNA damage, hypoxia was reported to influence CDC25A expression in colon cancer cells." (PMID 33925358, 2021). "It has been also shown that mR-21 negatively regulates Cdc25A and cell cycle progression in colon cancer cells." (PMID 27213347, 2016). "CDC25A, a G2/M checkpoint control gene is regulated by miR-21, a miRNA which has been shown to be under-expressed in subset of CDC25A over-expressing colon cancer samples." (PMID 25140888, 2014). "It appears that miR-21 targets multiple tumour-supressive pathways and recent studies showed convincing evidence that miR-21 negatively regulates Cdc25A and cell cycle progression in colon cancer and in human glioblastoma cells." (PMID 23216894, 2012). "Combined with these findings, we speculated that MMP1 might accelerate the cell cycle transition of colon cancer cells by regulating cdc25a/CDK4-cyclin D1 and p21/cdc2-cyclin B1 complexes through alteration in the expression of c-Myc and ETV4." (PMID 34753916, 2021). "In the present study, we demonstrated that MUM256 EA reduced the proliferation of colon cancer cells by arresting cells at G1 and G2 phases through the modulation of cell-cycle regulatory proteins including p21, cyclin B1, CDK2, CDK4 and cdc25A phosphatase." (PMID 31698795, 2019). "First, we found that NSC 95397 does not reduce the protein level of Cdc25A and the dephosphorylation of downstream protein Cdk1 in colon cancer cells." (PMID 29857489, 2018). "To further investigate the mechanisms involved in the inhibitory effect of NSC 95397 on colon cancer cells, we evaluated whether NSC 95397 inhibits Cdc25A and/or MKP-1 in colon cancer cells." (PMID 29857489, 2018). "However, in most of our experiments, 10 μM of NSC 95397 showed significant inhibitory activity on colon cancer cells without inhibiting the protein levels of Cdc25A and the Tyr-15 dephosphorylation of Cdk1." (PMID 29857489, 2018).
colorectal cancer (19 papers, 2010 to 2026). A primary or metastatic malignant neoplasm that affects the colon or rectum. "Interestingly, in APC-mutated-SK-UT-1 cells, endogenous CDC25A levels were higher than those found in two colorectal cancer cell lines with strong intrinsic Wnt signaling activity used as positive controls." (PMID 32911761, 2020). "CircDOCK1 (circ_0007142) upregulates CDC25A expression to promote colorectal cancer progression by sponging miR-122-5p." (PMID 38570856, 2024). "For instance, SIRT6 was shown to be lowly expressed in colorectal cancer stem cells, and its overexpression suppressed the cell proliferation, colony formation, and induced G0/G1 phase arrest in colorectal cancer stem cells via regulating CDC25A." (PMID 35251169, 2022). "In colorectal cancer cell lines, the ablation of the miR-21 gene was shown to induce an upregulation of CDC25A expression, which triggered cell cycle progression (G1-S and G2-M) and an increased proliferation." (PMID 34638467, 2021). "For example, circ_DOCK1 (hsa_circ_0007142) facilitated cell proliferation, migration, and invasion by modulating miR-122-5p/cell division cycle 25A (CDC25A) in colorectal cancer." (PMID 33685455, 2021). "Nek11, a member of the NIMA-related kinase family, phosphorylates Cdc25a and controls its degradation; Cdc25a phosphorylation is required for cell cycle progression in colorectal cancer cells." (PMID 23555558, 2013). "Depletion of Cdk2 with siRNA resulted in increased Cdc25A protein levels in human colorectal cancer cells." (PMID 20195506, 2010). "Moreover, Cdc25A is frequently found in many cancers, including in up to 53% of tumor samples from patients with colorectal cancer, suggesting that overexpression of Cdc25A might be associated with the development of colorectal cancer." (PMID 38277448, 2024). "Our results showed that CYT-Rx20 induced G2/M arrest in colorectal cancer cells with upregulated expression of cyclin B1, aurora A, and aurora B, and downregulated expression of cdc25A and cdc25C, which collectively could contribute to the inactivation of cdc2." (PMID 28178649, 2017). "We screened NCI-60 cell panel for BRE and CDC25A expression and selected prostate cancer cell line PC3 and colorectal carcinoma cell line SW620 for higher BRE and CDC25A expression." (PMID 29416040, 2018). "In addition, CYT-Rx20 induced cell cycle arrest of colorectal cancer cells at the G2/M phase and upregulated the protein expression of phospho-ERK, cyclin B1, phospho-cdc2 (Tyr15), aurora A, and aurora B, while it downregulated the expression of cdc25A and cdc25C." (PMID 28178649, 2017).
glioma (18 papers, 2010 to 2025). A benign or malignant brain and spinal cord tumor that arises from glial cells (astrocytes, oligodendrocytes, ependymal cells). "We will next continue to investigate the application of CDC25A in other glioma subtypes or therapeutic combinations." (PMID 39830513, 2024). "Possibly, the abundance of Cdc25a after miR-21 KO results in nuclear localization and increase in apoptosis in glioma cells." (PMID 35572197, 2022). "CDC25A has been reported as a positive regulator of the PI3K/Akt signaling pathway to promote the malignancy of glioma stem cells." (PMID 34266408, 2021). "qRT-PCR assays also demonstrated that CDC25A was upregulated in glioma tissues, in contrast to miR-195 expression but consistent with OXCT1-AS1 expression." (PMID 33832517, 2021). "OXCT1-AS1 inhibits glioma progression by regulating the miR-195-5p/CDC25A axis and is a specific tumour marker and a novel potential therapeutic target for glioma treatment." (PMID 33832517, 2021). "Up‐regulation of Linc00152 promotes malignant progression of glioma stem cells by regulating the miR‐103a‐3p/FEZF1/CDC25A pathway." (PMID 32307830, 2020). "Studies have shown that in the glioma stem cells (GSCs), CDC25A promotes tumor proliferation, migration, and invasion by promoting PI3K/AKT pathway and inhibits the apoptosis of GSCs." (PMID 32766313, 2020). "A previous study showed that inhibition of CDC25A expression induces apoptosis of human glioma cells, seemingly contradictory to upregulation of CDC25A during induction of apoptosis of U373MG cells in our study." (PMID 22494416, 2012). "CDC25A was correlated with poor prognosis in patients with low-grade gliomas." (PMID 39830513, 2024). "Subsequently, verify the effect of CDC25A on TMZ resistance in glioma cells." (PMID 39830513, 2024). "CDC25A affects TMZ resistance in glioma cells U251 and LN229." (PMID 39830513, 2024). "In addition, qPCR results has confirmed that the gene CDC25A was significantly higher expressed in glioma cells U251 and LN229 than in HEB cells (P<0.001, P<0.0001)." (PMID 39830513, 2024). "We further investigated the potential mechanism and found that OXCT1-AS1 may act as a ceRNA of miR-195 to enhance CDC25A expression and promote glioma cell progression." (PMID 33832517, 2021). "Furthermore, levels of Cdc25A Y59 phosphorylation correlate with grades of glioma malignancy and prognosis." (PMID 27485204, 2016). "In addition, we examined whether the levels of Cdc25A Y59 phosphorylation correlated with the grades of glioma malignancy." (PMID 27485204, 2016). "We assessed the protein levels of cdc25A, CDK2, and Cyclin A2 and found that the levels of these three proteins were reduced in glioma cells treated with PTE." (PMID 33737656, 2021). "Specifically, miR-125b regulates the proliferation of U251 glioma stem cells through the cell cycle-regulated proteins CDK6 and CDC25A." (PMID 23594394, 2013). "Our previous study showed that miR-125b is critical for the suppression of human U251 glioma stem cell proliferation through regulating the cell cycle proteins CDK6 and CDC25A." (PMID 23554660, 2010). "Our subsequent experiments confirmed that CDC25A may become a biomarker for evaluating TMZ resistance in gliomas, providing a new clinical treatment direction for drug-resistant glioma patients." (PMID 39830513, 2024). "Interestingly, FEZF1 was shown to upregulate the expression of the oncogenic gene CDC25A, activating the PI3K/AKT pathway and promoting the malignant behavior of glioma stem cells." (PMID 34830820, 2021). "Finally, it is worth mentioning that this study was conducted to experimentally validate the effect of gene CDC25A on temozolomide (TMZ) resistance, which is hoped to provide a reference for the individualized treatment of temozolomide-resistant glioma patients in the clinic." (PMID 39830513, 2024).
lung carcinoma (18 papers, 2015 to 2025). "One of limitations of this study is that the correlations between SNHG11 and miR-184, miR-184, and CDC25A have already been reported in other types of cancers, such as lung cancer and hepatic cancer." (PMID 33816469, 2021). "Further screening by establishing gene co-expression networks and preforming prognostic analysis identified CDK1, CCNB2, and CDC25A as the hub genes involved in lung cancer carcinogenesis and development." (PMID 34446056, 2021). "In our study, we found that levels of phosphorylated Chk1 were obviously increased, and Cdc25A was significantly decreased in NAT-F-treated lung cancer cells." (PMID 31619992, 2019). "We demonstrated that Chk1/Cdc25A pathway is involved in the regulation of DNA damage response in lung cancer cells exposed to NAT-F." (PMID 31619992, 2019). "In this study, we analyzed the expression and clinical significance of YBX1 and CDC25a in lung adenocarcinoma and identified their roles in the regulation of lung cancer growth." (PMID 27384875, 2016). "The upregulated expression of CLSPN and CDC25A is related to radioresistance in lung cancer." (PMID 33042838, 2020). "Transcriptome expression analysis from the GEPIA showed lung cancer tissues also exhibited higher NRAS, Cdc25a, CDK4, and γ-H2A.X expression." (PMID 38778121, 2024). "The protein expression levels of Cyclin E, cdc25A, ATM, p21, RRM2, γH2AX, and ATR/pATR were assessed via immunoblotting on samples from exponentially growing, untreated U2OS and lung cancer cells." (PMID 34359691, 2021). "Increasing evidence supports the crucial roles of CDC25A, BCL2, and c-Jun in promoting the proliferation, apoptosis, and radioresistance of lung cancer cells." (PMID 32943060, 2020). "In brief, we found that the USP7 was highly expressed concomitantly with the mitotic factors such as PLK1, CCNB1, CDC25A, and AURKB in prostate and lung cancer." (PMID 33207738, 2020). "Our study reveals that YBX1 activates CDC25a expression and suggests that the YBX1/CDC25a axis is involved in the cancer development and progression of human lung cancers." (PMID 27384875, 2016). "Collectively, these results demonstrate inhibition of YBX1 suppressed lung cancer growth partly via the CDC25a pathway and high expression of YBX1/CDC25a predicts poor prognosis in human lung adenocarcinoma." (PMID 27384875, 2016). "Subsequently, we found that knockdown of YBX1 by siRNA significantly decreased CDC25a activity and inhibited growth in vitro and in vivo, which indicated the key role of YBX1/CDC25a axis involved in lung cancer development and progression." (PMID 27384875, 2016). "Similarly, lung cancers are mostly suppressed by miR-184 via EPAS1, CDC25A, and c-MYC targeting, although chemotherapy resistance studies reveal occasional tumour-promoting roles." (PMID 41379397, 2025). "Higher NRAS, p-ERK1/2, and Cdc25a expression could be observed in LLC and A549, confirming that the NRAS signaling pathway was activated in lung cancer cells." (PMID 38778121, 2024). "Furthermore, our study revealed that MAP3K3 regulates the cell cycle through effects on CDC25A, CCND1/2 and CCNE1 regulation in lung cancer." (PMID 26088427, 2015).
cervical cancer (15 papers, 2018 to 2025). A primary or metastatic malignant neoplasm involving the cervix. "However, overexpression of miR-122-5p or suppression of CDC25A renders cervical cancer colonies unable to survive and causes them to undergo apoptosis." (PMID 36803831, 2023). "Consequently, miR-122-5p targets CDC25A, causing cervical cancer cells to become more radiosensitive." (PMID 36803831, 2023). "Taken together, these results showed that Cdc25A inhibited sorafenib-induced autophagy, which might be the mechanism underlying its role in cervical cancer cell ferroptosis." (PMID 34743185, 2021). "Another study reported that miR-122-5p enhances the radiosensitivity of cervical cancer cells by targeting CDC25A." (PMID 41373559, 2025). "Cervical cancer, a leading cause of cancer-related mortality in women, exhibits increased sorafenib resistance due to the Cdc25A/PKM2/ErbB2 pathway, in which Cdc25A suppresses ferroptosis by dephosphorylating PKM2 and upregulating ErbB2 expression." (PMID 41169372, 2025). "In contrast, ErbB2 acts as a negative regulator in cervical cancer, where its upregulation suppresses sorafenib-induced ferroptosis via the Cdc25A/PKM2 pathway." (PMID 40846695, 2025). "Conversely, in cervical cancer, Cdc25A enhances PKM2 dephosphorylation, which upregulates ErB2 expression and inhibits autophagy-induced ferroptosis." (PMID 39403142, 2024). "In cervical cancer tissues and cells, they revealed that miR-122-5p is poorly expressed while CDC25A is substantially expressed." (PMID 36803831, 2023). "USP7 was also found to extend the half-life of CDC25A by circumventing turnover, which stabilized CDC25A and enhanced resistance to DNA-damaging agents in cervical cancer." (PMID 36694209, 2023). "CDC25A inhibits autophagy-mediated ferroptosis by upregulating ErbB2 through PKM2 dephosphorylation in cervical cancer cells." (PMID 36072430, 2022). "This work focused on the function of CDC25A in cervical cancer cell growth and the molecules involved." (PMID 34266408, 2021). "To further validate the correlation between CDC25A and cervical cancer progression, we further explored the CDC25A expression in TCGA-CESC (data of CESC tissues) and GTEx-Cervix (data of normal cervical tissues) in the GEPIA database." (PMID 34266408, 2021). "In this paper, cell division cycle 25A (CDC25A) was predicted as a candidate oncogene in cervical cancer according to the integrated bioinformatics analyses." (PMID 34266408, 2021). "Collectively, these results indicated that CDC25A plays an oncogenic role in cervical cancer progression." (PMID 34266408, 2021). "Together, these results showed that sorafenib induced ferroptosis in cervical cancer cells and downregulated Cdc25A expression levels." (PMID 34743185, 2021). "Cdc25A suppressed autophagy-dependent ferroptosis in cervical cancer cells by upregulating ErbB2 levels through the dephosphorylation of PKM2." (PMID 34743185, 2021). "In the present study, we sought to examine the role of ferroptosis in cervical cancer, with a focus on the Cdc25A/ErbB2 axis." (PMID 34743185, 2021). "In our study, we found that Cdc25A suppressed sorafenib-induced ferroptosis and promoted cervical cancer cell growth by dephosphorylating PKM2 in the nucleus." (PMID 34743185, 2021). "Cdc25A was elevated in human cervical cancer tissues but was reduced during sorafenib-induced ferroptosis of cervical cancer cells." (PMID 34743185, 2021). "Taken together, these data showed that overexpression of Cdc25A in cancer cells inhibited cervical cancer cell ferroptosis." (PMID 34743185, 2021). "Here, we investigated the role of ferroptosis in cervical cancer, with a focus on the Cdc25A/PKM2/ErbB2 axis." (PMID 34743185, 2021). "To study the function of Cdc25A in cervical cancer, we first measured its expression level in cervical cancer tissues." (PMID 34743185, 2021). "A similar trend was obtained from the GEPIA database, where higher expression of CDC25A was predicted in the cervical cancer tissues." (PMID 34266408, 2021).